EGFR (epidermal growth factor receptor)
Diseases named in the same sentence as EGFR in open-access papers (continued):
Sharing a sentence is not in itself a finding about the gene and the disease.
gastric cancer (continued). "SRC plays an important role in the migration of gastric cancer cells by mediating a potential CXCR4-EGFR crosstalk and sequentially activating the EGFR-Akt/ERK axis." (PMID 36299773, 2022). "Of these EGFR alterations, amplification of EGFR was less frequent in SBA and CRC (1.6% of cases each) as compared to gastric cancer (3.4% of cases)." (PMID 35267592, 2022). "However, subgroups of gastric cancer patients may benefit from anti-EGFR treatment." (PMID 35264144, 2022). "We found that GCA shares some common oncogene focal amplifications with both gastric cancer and esophageal cancer including CCNE1, EGFR, and MYC." (PMID 34764264, 2021). "In gastric cancer cells NCI-N87, a knockdown of FUT1 expression via shRNA led to reduced expression of Lewisy on EGFR." (PMID 34069424, 2021). "It was known that mutations in genes such as CDH1, PIK3CA, ARID1A (AT-rich interactive domain 1A), EGFR, and PTEN existed in gastric cancer, providing potential circulating DNA for detection of gastric cancer." (PMID 33693004, 2021). "The treatment of EGFR and HER2 overexpressing gastric cancer cells with Afatinib (a pan-ErbB2 family TKI) and lapatinib (EGFR, ErbB2 inhibitor) reduced PD-L1 expression levels." (PMID 33807608, 2021). "Gastric cancer cells are insensitive to TRAIL, but inhibition of epidermal growth factor receptor activation and redistribution in lipid rafts can increase the sensitivity and therefore stimulate apoptosis." (PMID 33450869, 2021). "In gastric cancer, S1P, SphK1 synthesizes binds to S1PR2 and transactivates two potent RTKs, EGFR and c-Met." (PMID 33920887, 2021). "In human AGS gastric cancer cells, uPAR can be stimulated by prostaglandin E2 via the EP2 receptor-dependent Src/EGFR/JNK1/2, Erk1/2/AP-1, Src/EGFR/JNK1/2, and Erk1/2/NF-κB signaling pathways, thereby promoting tumor metastasis." (PMID 34729105, 2021). "In the PANGEA phase II trial, a personalized treatment strategy was applied in gastric cancer patients: antibodies targeting HER2, MET, FGFR2 EGFR PD-L1 or VEGFR2 were added to chemotherapy in first- to third-line treatment in gastric or GEJ cancer patients." (PMID 34680363, 2021). "Transactivation of EGFR by TGF-β signaling has also been documented in breast, gastric cancer cells, and hepatocytes." (PMID 33246423, 2020). "KRAS, PI3K and EGFR proteins are connected within a common signal transduction pathway, highlight the importance of the EGFR/MAPK pathway for the development of gastric cancer." (PMID 32698506, 2020). "Our findings indicate that ASTX can suppress H. pylori-induced gastric cancer progression by inhibiting cytoskeleton reorganization and reducing cell motility through downregulation of c-MET, EGFR, PI3KC2, PLCγ1, Cdc42, and ROCK1." (PMID 32679742, 2020). "Nonetheless, the overexpression of EGFR and HER2 has been demonstrated to significantly impact the prognosis, survival rate, and targeted therapy selection in patients with advances gastric cancer." (PMID 32850413, 2020). "Poziotinib is significantly more potent than other EGFR inhibitors, such as BIBW-2992, gefitinib and lapatinib, in inhibiting the proliferation of gastric cancer cells that overexpress the HER2 protein." (PMID 33158067, 2020). "This provides a new theoretical basis for the combination of the EGFR monoclonal antibodies including cetuximab, PD-L1 inhibitors, and human recombinant TRAIL in gastric cancer therapy and can filter patients who are currently sensitive to TRAIL treatment." (PMID 32775300, 2020). "In gastric cancer AGS cells, xenograft SCID mice were treated with Tan IIA for 8 weeks, which significantly decreased the expression levels of epidermal growth factor receptor (EGFR), IGFR, PI3K, AKT, and mTOR proteins in dose-dependent fashion." (PMID 36046197, 2020).
gastric cancer (continued). "In conclusion, ASTX can suppress H. pylori-induced gastric cancer progression by inhibiting cytoskeleton reorganization and reducing cell motility through downregulation of c-MET, EGFR, PI3KC2, PLCγ1, Cdc42, and ROCK1." (PMID 32679742, 2020). "Curcumin inhibits Bcl-2, Bcl-XL, VEGF, c-Myc, ICAM-1, EGFR, STAT3 phosphorylation, and cyclin D1 genes involved in the various stages of breast, prostate, and gastric cancer proliferation, angiogenesis, invasion, and metastasis." (PMID 33178666, 2020). "The EGFR-mediated PI3K/AKT signal pathway promotes proliferation of gastric cancer through LINC00152, which directly binds to the EGFR protein." (PMID 33050646, 2020). "Genomic alterations in RTKs, including EGFR, HER2, FGFR2, and MET, were reported to occur in ~37% of gastric cancer patients." (PMID 32005975, 2020). "Our study revealed that CD148 exerted onco-suppressing function by dephosphorylating EGFR on Y1173, Y1068, and Y1092 and inhibiting the MEK/ERK and PI3K/AKT pathways in gastric cancer." (PMID 32201537, 2020). "In human gastric carcinoma cells (AGS), the activation of TGR5 by deoxycholic acid triggers the activation of ERK1/2, MAPK, and the epidermal growth factor receptor (EGF-R), and its silencing promotes apoptosis." (PMID 33113952, 2020). "Taken together, these observations suggest that EGFR inhibitor attenuates CD44v protein expression though an AKT-dependent and ERK-dependent pathway, which reduces the therapy-resistant gastric cancer subpopulation." (PMID 31607750, 2019). "Subsequent studies have shown that M3R signaling promotes cellular proliferation and inhibits apoptosis via the epidermal growth factor receptor (EGFR) and Akt pathways in human gastric cancer cell lines and xenografts." (PMID 31405140, 2019). "The present study was carried out to examine the effect of lycopene on proliferation and apoptosis and to determine the impact of lycopene on the levels of cellular ROS, activated EGFR and Ras, MAPKs and COX-2 in gastric cancer AGS cells." (PMID 31491956, 2019). "In a previous study, surface glycoproteins on MKN28 gastric cancer cells that directly interact with PFL were isolated and identified as integrin α2 and EGFR." (PMID 31052260, 2019). "A recent study has shown that some gastric cancer cell lines including AGS are resistant or partially resistant to treatment of cetuximab, an inhibitory EGFR antibody for treatment of metastatic colorectal cancer, on EGF-stimulated cell migration and invasion." (PMID 30976198, 2019). "Despite the use of VEGF-, EGFR-, and HER2-targeting agents, prognosis is still poor in advanced gastric cancer." (PMID 30881447, 2019). "In total, 20% of gastric cancers were either MET-, EGFR- and HER2- positive or MET- and EGFR- or HER2-positive." (PMID 31557260, 2019). "It is well known that gastric cancer overexpresses HER in a heterogeneous pattern, especially EGFR, and HER2." (PMID 31850207, 2019). "We previously reported that PFL induced cell death accompanying EGFR/integrin internalization and subsequent autophagy in MKN28 gastric cancer cells." (PMID 31052260, 2019). "Taken together, these studies have demonstrated the involvement of the EGFR/Ras/MAPK signaling pathway in the activation of NF-κB, the induction of COX-2, and the proliferation of gastric cancer cells." (PMID 31491956, 2019). "To confirm whether EGFR inhibition-mediated CD44v downregulation could cause the CD44v9-expressing cell-selective growth inhibition, we examined the effect of CD44 knockdown on the proliferation of CD44v9-positive and CD44v9-negative cells sorted from the gastric cancer PDCs." (PMID 31607750, 2019). "Genetic alterations in the EGFR, MET, ERBB2, and the PI3K/AKT pathway are often observed in gastric cancer." (PMID 31816819, 2019). "The two HER2-amplified gastric cancer cell lines NCI-N87 and SNU-216 were sensitive to EGFR tyrosine kinase inhibitor lapatinib." (PMID 31557260, 2019).
gastric cancer (continued). "We observed synergistic effects on KatoIII cells as well as three additional gastric cancer cell lines with FGFR2 amplification when AZD4547 was combined with small molecular inhibitors Cpd22 and lapatinib targeting ILK and EGFR/HER2, respectively." (PMID 31076567, 2019). "High expression levels of EGFR and CXCR4 mRNA and protein were observed among primary tumours and human gastric cancer cell lines, with an upraised possibility to evoke peritoneal carcinomatosis." (PMID 29867026, 2018). "In our cohort, the rates of gastric cancers positive for E-cadherin, Ki67, VEGFR2 and EGFR expressions were 34.3% (35/102), 51.5% (70/136), 47.7% (63/132) and 32.8% (44/134), respectively." (PMID 30087428, 2018). "Epidermal growth factor receptor (EGFR) is one of the tyrosine kinase receptors (RTKs) and plays an important role in the occurrence and development of gastric cancer." (PMID 30524285, 2018). "In the process of gastric cancer cell migration, EGF activates EGFR, which through the combination of Grb2 and DENND1A plays a role in target molecule activation and targeted recruitment." (PMID 30524285, 2018). "The different effect of EGFR or HIF-1α mRNA in breast, ovarian, lung, and gastric cancer was also demonstrated by the Kaplan-Meier Plotter algorithm, which documents the different tissue-specific prognostic effect of both markers." (PMID 30513863, 2018). "In this study we demonstrated for the first time that EGF stimulates EGFR and activates Rab35 via DENND1A in gastric cancer cells." (PMID 30524285, 2018). "Although we found a differential expression of EGFR, FGFR2, KLF4, DNMT1 and AGO4 in gastric cancer samples, only FGFR2 overexpression was statistically significant (P = 0.0449)." (PMID 29719612, 2018). "Knockdown of NEDD4 severely impaired EGF-stimulated gastric cancer cell migration and invasion, suggesting that NEDD4 mediates migration and invasion signaling of EGFR." (PMID 29455656, 2018). "Recently, therapies targeting human epidermal growth factor receptor-2 (HER-2), epidermal growth factor receptor (EGFR), vascular endothelial growth factor (VEGF) and so on, have provided gastric cancer patients with better survival rates." (PMID 30541591, 2018). "EGFR/HER2 pathway signaling and PD-L1 expression in gastric cancer cell lines were screened by western blot analysis." (PMID 28969039, 2017). "TFF3 has previously been reported to induce tyrosine phosphorylation and activation of EGFR and HER2 in a colonic epithelial cell line (HT-29), gastric cancer cell line (AGS) and oral keratinocytes." (PMID 29088778, 2017). "These mapped with high statistical significance to ten canonical signaling pathways, all of which were less active in low DOK6 gastric cancers: gastrin-CREB, NGF, PDGF, EGFR, ERKs, ERBB4, FGFR2, RAS, VEGFR2 and RAF/MAP kinase." (PMID 29872697, 2017). "Multiple oncogenic signaling pathways (gastrin-CREB, NGF-neurotrophin, PDGF, EGFR, ERK, ERBB4, FGFR1, RAS, VEGFR2 and RAF/MAP kinase) known to be active in aggressive gastric cancers were strikingly diminished in gastric cancers with low DOK6 expression." (PMID 29872697, 2017). "Similar findings demonstrating intra-tumor and intra-sample heterogeneity of receptor tyrosine kinase amplification (including HER2, EGFR and FGFR2) expression in gastric cancer, have previously been reported." (PMID 29340092, 2017). "EGFR, ERBB3/HER3, VEGF, PI3K/mTOR, FGFR2 and MET show promise as new targets for gastric cancer treatment." (PMID 29237412, 2017). "In other cell lines, such as MET‐addicted gastric carcinoma MKN45 and EGFR‐addicted CRC SW48 lines, where oncogene inhibition only blocked proliferation, HSP27 knockdown made targeted agents switch from cytostatic to cytotoxic activity." (PMID 28182330, 2017). "Several studies investigating target genes such as EGFR, MET, and fibroblast growth factor receptor (FGFR) have been conducted since the application of trastuzumab in the treatment of HER2-positive gastric cancer patients." (PMID 27765925, 2016).
gastric cancer (continued). "A recent genomic study of gastric cancers identified somatic copy number alterations of seven oncogenes involved in tyrosine kinase/MAP-kinase pathways: KRAS, EGFR, HER2, FGFR1, FGFR2, MET and IGF1R." (PMID 27437872, 2016). "NRP-1 depletion counteracted the activation of VEGF/VEGFR2, EGF/EGFR and HGF/c-Met pathways stimulated by respective ligands, indicating that NRP-1 acts as multifunctional co-receptors in gastric cancer cells." (PMID 26795388, 2016). "EHF expression was significantly positively correlated with the expression of EGFR (R=0.43; P=0.018), HER2 (R=0.51; P=0.004) and HER3 (R=0.39; P=0.034) in gastric cancers." (PMID 27787520, 2016). "By summarizing data on HER2, VEGR, EGFR, mTOR, MET, and other common cancer targets or signaling pathways, this review attempts to expound the advance of molecular targeted therapy for gastric cancer in recent years." (PMID 26880889, 2016). "NRP-1 is shown to participate as co-receptors in the activation of the VEGF/VEGFR2, EGF/EGFR and HGF/c-Met pathways, which play key roles in the proliferation and metastasis of gastric cancer cells." (PMID 26795388, 2016). "Amplification of seven oncogenes: HER2, EGFR, FGFR1, FGFR2, MET, KRAS and IGF1R has been identified in gastric cancer." (PMID 27437872, 2016). "Given the proposed involvement of EGFR and HER2 signaling in some gastric cancers and previously-reported crosstalk between the Hh and EGFR pathways, we determined the expression levels of Egfr, Her2, and Egfr ligand mRNAs by real-time PCR." (PMID 26859571, 2016). "Cetuximab, an antibody that targets the EGFR, and erlotinib, an EGFR-targeting small molecule tyrosine kinase inhibitor (TKI) are currently under clinical evaluation in gastric cancer trials." (PMID 27738318, 2016). "The activation of EGFR pathway leads to the phosphorylation of MEK and ERK, which contributes to the proliferation and metastasis of gastric cancer cells." (PMID 26795388, 2016). "Subsequently, more anti-EGFR and anti-VEGFR target drugs were used for the treatment of advanced gastric cancer." (PMID 27633381, 2016). "Other phase I trials seek to test combinations of volitinib and docetaxel in gastric cancer (NCT02252913) and volitinib and gefitinib for EGFR TKI-resistant NSCLC in patients with mutant EGFR (NCT02374645)." (PMID 27013592, 2016). "Receptor tyrosine kinase (RTK)-related genes, including HER2, EGFR, MET, FGFR2 and KRAS, are target molecules that are clinically beneficial in gastric cancer (GC)." (PMID 27014419, 2016). "An abnormally high expression of EGFR and HER-2 has been identified in gastric cancer cells, colorectal cancer cells and esophageal squamous cell carcinoma cells." (PMID 26728266, 2016). "Mechanistic investigations concluded that DARPP-32 promotion of EGFR/ERBB3 protein interaction leads to EGFR phosphorylation and activation of PI3K-AKT signaling, thereby increasing cell survival and gefitinib resistance in gastric cancer cells." (PMID 26872373, 2016). "When gastric cancer cells were treated with berberine(72h IC50) for 72 hours, the level of phosphorylation of EGFR also decline, but EGFR remained unaffected." (PMID 27738318, 2016). "Since the knockdown of CD24 by siRNA inhibited EGFR expression, we further analyzed the effect of CD24 on EGFR related signaling pathway in gastric cancer cells." (PMID 26830684, 2016). "Among 41 gastric cancer cases, we found that both CD24 and EGFR expression level was markedly increased in low-differentiated tumor tissues when compared with their matched highly-differentiated tumor tissues." (PMID 26830684, 2016). "Second, increased phosphorylation of other RTKs, including EGFR, was also shown in GALNT2 knockdown gastric cancer cells." (PMID 26848976, 2016). "In the present study, we demonstrated that the high mannose binding bacterial lectin PFL induced rapid intracellular trafficking of both EGFR and α2 integrin in MKN28 gastric cancer cells." (PMID 26850110, 2016).
gastric cancer (continued). "Only 2.1 % (1/48) of patients showed 2+/3+ expression of both EGFR and HER-2, suggesting there is little overlap between EGFR and HER-2 overexpression in gastric cancer." (PMID 25185971, 2015). "Previously, we compared the results of an nCounter assay with immunohistochemistry results using three biomarkers (EGFR, HER2 and MET) in a gastric cancer (GC) model." (PMID 26486455, 2015). "In order to determine the optimal therapeutic target for future studies, the question that needs to be resolved is which of EGFR, FGFR2, and NKX2.1 is the most upstream and the critical alteration in primary gastric cancer." (PMID 25154973, 2015). "Overexpression of ErbB1 (EGFR) and ErbB2 (HER-2) is found in 27–64% and 6–34% of gastric cancer, respectively." (PMID 25945346, 2015). "Epidermal growth factor receptor (EGFR), a member of ErbB receptor family, is involved in the regulation of gastric mucosal cell proliferation and progression of gastric cancer." (PMID 25945346, 2015). "Distribution of clinical and pathological factors of correlation with EGFR and univariate prognostic analysis in 167 pStage II/III gastric cancer with gastrectomy and subsequent S-1 treatment." (PMID 25154973, 2015). "However, the clinical significance of EGFR (c-erbB1) in gastric cancer remains unclear." (PMID 24348859, 2014). "The EGFR and the EGF-family of peptide growth factors play an important role in the development and progression of diverse carcinoma types, including gastric cancer." (PMID 23420566, 2013). "In the present study, a EGFR/CD3 BsAb was produced and the cytotoxicity of CIK cells targeted by this BsAb to gastric cancer cells was investigated." (PMID 23833649, 2013). "The present study revealed that in gastric cancer cells, PKG II is able to inhibit the EGF/EGFR-induced signal transduction of the PI3K/Akt-mediated pathway and reverse the anti-apoptotic effects of EGF/EGFR." (PMID 24273605, 2013). "The results indicate that the EGFR/CD3 BsAb is able to enhance the ability of CIK cells to bind to and kill gastric cancer cells in vitro and in vivo." (PMID 23833649, 2013). "H. pylori CagL-Y58/E59, the gastric cancer strain inducing gastric epithelial cells to have greater CagA translocation, IL-8 secretion, as well as to have higher integrin β1, FAK, EGFR and AKT activation than H. pylori CagL-Y58D/E59K did." (PMID 24009701, 2013). "In vitro studies showed that activation of PAR-2 enhances the growth of two gastric cancer cell lines AGS and MKN28 via EGFR trans-activation." (PMID 24146905, 2013). "In GC, the expression of EMT-related proteins and the overexpression of EGFR using TMAs were correlated with a poor prognosis and TMA protein expression profiling predicts LN metastasis and prognosis in early stage gastric cancer." (PMID 23545944, 2013). "Studies presented here support a role for Cbl-b E3 ubiquitin ligase in promoting chemosensitivity of gastric cancer cells to 5-FU through a mechanism that involves Cbl-b-dependent limitation of ERK and Akt survival signaling downstream of EGFR." (PMID 24351824, 2013). "The combination effects of two EGFR inhibitors, gefitinib and lapatinib, with SN38 on proliferation, apoptosis, and cell cycle on gastric cancer cells were examined." (PMID 21997136, 2011). "This study was performed to clarify the effect of epidermal growth factor receptor (EGFR) inhibitors in combination with SN38, an active metabolite of irinotecan, on the proliferation of irinotecan-refractory gastric cancer." (PMID 21997136, 2011). "In certain gastric cancer cell lines, SN38, an active metabolite of irinotecan, has been shown to induce the tyrosine phosphorylation of EGFR, which are considered to be involved in the development of drug resistance to irinotecan." (PMID 21997136, 2011). "Aberrant expression of EGFR or VEGF and amplification of HER2 or c-MET have been described to be useful for clinical prognosis of gastric cancer." (PMID 27030788, 2011).